MPRIP (myosin phosphatase Rho interacting protein)
Description:
Targets myosin phosphatase to the actin cytoskeleton. Required for the regulation of the actin cytoskeleton by RhoA and ROCK1. Depletion leads to an increased number of stress fibers in smooth muscle cells through stabilization of actin fibers by phosphorylated myosin. Overexpression of MRIP as well as its F-actin-binding region leads to disassembly of stress fibers in neuronal cells.
Synonyms: M-RIP; RIP3; MRIP; RHOIP3; p116Rip
Tractability: PROTAC: ubiquitination databases record sites on it; its protein half-life has been measured.
Gene: Protein-coding gene on chromosome 17 (17,042,457 to 17,217,679, forward strand). Ensembl gene ENSG00000133030.
Subcellular location: Cytoplasm, cytoskeleton
Subcellular location (Human Protein Atlas): Actin filaments; Cytosol
Pathways (Reactome):
Disease: Signaling by BRAF and RAF1 fusions
Gene Ontology:
Molecular function: cadherin binding; protein binding; actin filament binding
Cellular component: actin cytoskeleton; focal adhesion; cytoskeleton
Genetic constraint (gnomAD): Loss-of-function variants: 38 observed, 173.74 expected, observed/expected ratio (o/e) 0.22, 90% interval 0.17 to 0.29. The upper end of that interval is the gene's LOEUF score, 0.29, which puts it in group 1 of 6, group 1 being the genes least tolerant of losing a copy. Missense variants: 1,739 observed, 2,262.6 expected, observed/expected ratio (o/e) 0.77, 90% interval 0.74 to 0.8. Synonymous variants: 834 observed, 935.6 expected, observed/expected ratio (o/e) 0.89, 90% interval 0.84 to 0.94.
Homologues: Orthologues: macaque MPRIP (93% identical), dog MPRIP (84% identical), rat Mprip (81% identical), rabbit MPRIP (81% identical), guinea pig MPRIP (78% identical), mouse Mprip (76% identical), tropical clawed frog mprip (52% identical), chimpanzee MPRIP (41% identical), zebrafish si:ch73-103b11.2 (20% identical), Drosophila melanogaster osp (15% identical), Caenorhabditis elegans F10G8.8 (11% identical). Paralogues in human: TRIOBP (16% identical).
Diseases named in the same sentence as MPRIP in open-access papers:
MPRIP is named in the same sentence as 26 diseases in open-access papers, as found by Europe PMC text mining. Sharing a sentence is not in itself a finding about the gene and the disease. The quoted sentences say what the papers report.
lung carcinoma (2 papers, 2014 to 2018). "NTRK1 (Neurotrophic Receptor Tyrosine Kinase 1; encodes TrkA) was previously reported to impose oncogenic activity in lung cancer cells by fusing with CD74 and, independently, with MPRIP." (PMID 29568375, 2018). "In particular, NTRK1 has been found to fuse with tropomyosin in colon cancer, TPM3, TPR, and TFG in thyroid cancer, and MPRIP and CD74 in lung cancer." (PMID 24647444, 2014).
autoimmune disease (1 paper, 2021). A disorder resulting from loss of function or tissue destruction of an organ or multiple organs, arising from humoral or cellular immune responses of the individual to their own tissue constituents. "Also, the interaction between the Ragulator complex and MPRIP represents a therapeutic target for autoimmune diseases and inflammation by inhibiting leukocyte motility." (PMID 34099704, 2021).
diabetic retinopathy (1 paper, 2020). "Similarly, several genes implicated in diabetic retinopathy – classically considered a retinal vasculopathy– were differentially expressed by RGCs (e.g AKR1B1, HS6ST3 and MPRIP), suggesting that a primary neuropathic process may also be involved." (PMID 32555229, 2020).
lung adenocarcinoma (1 paper, 2017). A carcinoma that arises from the lung and is characterized by the presence of malignant glandular epithelial cells. "To evaluate the possibility for clinical application, we tested the expression of DNAJB1, MCU, MPRIP, PSAP, RAI14, ZNF131 and TMC5 in 71 lung adenocarcinoma samples and paired adjacent normal tissue samples (>2 cm away from the tumor) from patients who underwent lobectomy or pneumonectomy." (PMID 29285248, 2017).
neuroblastoma (1 paper, 2020). Neuroblastoma (NB) is the most common solid, extracranial childhood tumor. "Moreover, analysis of the TRPM7-associated interactome in neuroblastoma cells identified proteins which were mainly related to the actin cytoskeleton, such as Myosin IIA, Drebrin and the Myosin phosphatase Rho-interacting protein (p116RIP)." (PMID 33240883, 2020).
Osteopenia (1 paper, 2023). Osteopenia is a term to define bone density that is not normal but also not as low as osteoporosis. "Simultaneously, MPRIP variants might distort cytoskeleton and morphology, leading to osteopenia, eventually collapse and ischemic necrosis of the femoral head." (PMID 36813871, 2023).
papilloma (1 paper, 2023). A benign epithelial neoplasm that projects above the surrounding epithelial surface and consists of villous or arborescent outgrowths of fibrovascular stroma. "The result showed that papilloma carried higher mutation rate of genes, such as MPRIP, HRAS, and MAP3K1, while PUC carried a higher mutation rate of genes, such as FGFR3 and PPFIBP1 (Fisher’s exact test, p < 0.05)." (PMID 37704624, 2023). "We also investigated the protein expression level of these mutations, the results showed four proteins (HRAS, ALDH7A1, CBLB, and MPRIP) were differently expressed between papilloma and PUC." (PMID 37704624, 2023).
psychosis (1 paper, 2019). "Bioinformatic analysis of WES and CGH-array data selected 15 common for psychosis phenotype damaging variants and 6 of them were rare mutations, including paternal 3p26.3-loss and 5 additional missense mutations located in ACSF2, MPRIP, PHC1, PER3, and RERE genes." (PMID 30710087, 2019).
thrombosis (1 paper, 2023). "Notably, FGA, VWF and MPRIP variants correlated with intravascular coagulation and thrombosis, as well as impaired mechanosensory functions of osteocytes." (PMID 36813871, 2023).
urothelial papilloma (1 paper, 2025). A rare benign condition, characterized by a papillary growth in the urinary tract with a central fibrovascular core. "Therefore, urothelial papilloma shows a higher mutation rate in MPRIP, HRAS, and MAP3K1 genes, whereas papillary UC carries mutations in FGFR3 and PPFIBP1." (PMID 40227699, 2025). "HRAS, ALDH7A1, CBLB, and MPRIP proteins are differently expressed in urothelial papilloma and papillary UC." (PMID 40227699, 2025).
cancer (4 papers, 2017 to 2024). A tumor composed of atypical neoplastic, often pleomorphic cells that invade other tissues. "In a variety of cancers, these 4 up-regulated genes (DNAJB1, MCU, MPRIP and PSAP) have been reported to be related to drug-resistance processes, cell death, cancer invasion and metastasis." (PMID 29285248, 2017). "In 38 tumor-specific SE-associated genes, 37 genes showed significantly elevated expression in at least 1 cancer cell line, including DNAJB1, MCU, MPRIP and PSAP." (PMID 29285248, 2017).
tumor (3 papers, 2017 to 2024). "The amount of skipped MPRIP isoform was higher in metastatic PDA samples (lower PSI) compared with primary tumours." (PMID 36949200, 2023). "We next tested whether modulation of MPRIP splicing could affect the metastatic potential of PDA tumour cell lines." (PMID 36949200, 2023). "Six rare fusion partners were also identified: GOPC, MPRIP, NUP210L, ZCCHC8, CCDC6, and CFAP53, each present in one tumor." (PMID 38835380, 2024). "In 41 tumor-specific SEs, several SEs with significant H3K27ac enrichment were close to previously reported tumor-related genes, like MCU, MPRIP and PSAP (Supplementary-2)." (PMID 29285248, 2017).
neurological diseases (1 paper, 2020). "HNRNPDL and RBM39 function in transcriptional regulation, HNRNPDL and SRSF2 regulate alternative splicing, MPRIP is involved in stress granule formation, CHID1 has a role in pathogen sensing, and KIF21A has been implicated in neurological diseases." (PMID 32380717, 2020).
MPRIP also shares sentences with these, for which no sentence is quoted: breast cancer (2 papers); bladder cancer (1); cervical cancer (1); cervical tumors (1); colon cancer (1); glioma (1); Hypertension (1); Insulin resistance (1); osteonecrosis (1); Parkinson disease (1); pterygium (1); thyroid cancer (1); ZIKV infection (1).